RAB25 (RAB25, member RAS oncogene family)
Diseases named in the same sentence as RAB25 in open-access papers (continued):
Sharing a sentence is not in itself a finding about the gene and the disease.
lung carcinoma (4 papers, 2010 to 2019). "Knockdown of Rab25 was found to reduce anti-apoptotic protein, Bcl-2, in tobacco carcinogen-induced lung cancer." (PMID 28969096, 2017). "Knockdown of Rab25 was reported to inhibit tumor growth in tobacco carcinogen-induced lung cancer model." (PMID 28969096, 2017). "The effects of Rab25 knockdown on tumor proliferation and apoptosis were also confirmed in mice xenografted with gefitinib-sensitive lung cancer cells with wtEGFR." (PMID 24658031, 2014). "Rab25 knockdown caused the changed EGFR endocytosis and reverted the gefitinib response in gefitinib-sensitive lung cancer with wtEGFR in vitro and in vivo." (PMID 24658031, 2014). "Therefore, our findings indicate that Rab25 plays a crucial role in EGFR signaling in lung cancer with wtEGFR." (PMID 24658031, 2014). "In addition, we identified that EGFR endocytosis-related Rab25 expression is crucially considered when patients with lung cancer and wtEGFR are treated with gefitinib." (PMID 24658031, 2014). "Moreover, we demonstrated that silencing Rab25 reversed the sensitivity to gefitinib in gefitinib-sensitive lung cancer cells expressing normally." (PMID 24658031, 2014). "In addition, we found that Rab25 was differentially expressed in between gefitinib-sensitive and -insensitive lung cancer cells." (PMID 24658031, 2014). "In the present study, we determined that Rab25 regulated EGFR endocytosis, and its expression status was significantly correlated with the response of gefitinib in lung cancer with wtEGFR." (PMID 24658031, 2014). "However, the precise role of Rab25 in lung cancer remains unclear." (PMID 24658031, 2014). "Next, to evaluate whether the expression status of Rab25 is associated with the response to gefitinib in lung cancer with wtEGFR, we performed a comparative analysis between Rab25 expression and IC50 values to gefitinib in eight lung cancer cell lines." (PMID 24658031, 2014). "Second, we did not evaluate Rab25 function in patients with lung cancer and wtEGFR who did not have a response to gefitinib." (PMID 24658031, 2014).
ovarian tumor (4 papers, 2010 to 2020). "Interestingly, the loss of expression of RAB25 is associated with subtypes of breast or ovarian tumors displaying a mesenchymal phenotype." (PMID 24403269, 2013). "Rab25 knockdown by shRNA shows less proliferation, more apoptosis, and decreased ovarian tumor growth both in vitro and in vivo." (PMID 21143914, 2010). "However, Rab25 is associated with elevated CLIC3 in both cultured A2780 cells and in pancreatic and ovarian tumors, and CLIC3 functions to return lysosomally targeted α5β1 to the plasma membrane, thus opposing receptor degradation." (PMID 22197222, 2012). "Further in vivo studies confirmed that expression of Rab25 increases ovarian tumor growth." (PMID 21143914, 2010). "Rab25 directly interacts with AKT and Rab25 levels are positively correlated with activated AKT levels in ovarian tumor samples." (PMID 31973201, 2020).
prostate carcinoma (4 papers, 2017 to 2022). A carcinoma that arises from epithelial cells of the prostate gland. "Indeed, in various cancer types (e.g., bladder, non-small cell lung, ovarian, prostate cancer, and clear cell renal cell carcinoma), RAB25 overexpression has been associated with shorter overall survival." (PMID 34771571, 2021). "Another study indicated that it serves as a sponge for miR-338-3p to promote prostate cancer progression by regulating Rab25." (PMID 36213821, 2022). "Knockdown of Rab25 expression by siRNA / shRNA transfection inhibited in vitro cell growth of renal cell carcinoma cells (786-O and A-498), prostate cancer cells (LNCaP) and hepatocellular carcinoma cells (Bel7402 and SK-Hep-1)." (PMID 28969096, 2017). "We aimed to investigate clinical significance of Rab25 in prostate cancer (PCa)." (PMID 28400705, 2017).
Pancreatic cancer (3 papers, 2012 to 2017). "Pancreatic cancer patients with high Rab25 and high CLIC3 levels were associated with significantly shorter survival time." (PMID 28969096, 2017). "In pancreatic cancer, Rab25 acts as an oncogene in the presence of CLIC3, whereas, Rab25 acts as a tumor suppressor in the absence of CLIC3." (PMID 28969096, 2017). "RAB25 and RAB27 have been reported to be expressed in cancer cells and to promote cancer progression in pancreatic cancer." (PMID 28103577, 2017). "Indeed, although the correlation between Rab25 and CLIC3 in pancreatic tumors is highly statistically significant, this relationship is not hard and fast, and there are many tumors that express Rab25 that do not express CLIC3 and vice versa." (PMID 22197222, 2012).
oropharyngeal squamous cell carcinoma (2 papers, 2017 to 2021). "RAB25, a member of the Rab11 small GTPase family, mediates cancer progression, and is downregulated in oral and oropharyngeal squamous cell carcinoma." (PMID 34868916, 2021). "In the study of oral and oropharyngeal squamous cell carcinoma (OOSCC), lower Rab25 expression was associated with lymph node metastasis status." (PMID 28969096, 2017).
ovarian serous carcinoma (2 papers, 2021). "Another study assessed the protein expression of E-CADH, N-CADH, P-cadherin, ZEB1, HMGA2, RAB25, CD24, NCAM, SOX11, and VIM in 100 tubo-ovarian serous carcinoma effusions and found a limited prognostic role of the markers alone or in combination." (PMID 34070214, 2021). "Analysis of the ovarian serous carcinoma dataset showed that of 398 patients, amplification of TPD54 was seen in 29 (7%), amplification of Rab25 in 20 (5%), and a significant cooccurrence in 7 patients (log2 odds ratio >3, P < 0.001, and q < 0.001)." (PMID 34287617, 2021).
renal cell carcinoma (2 papers, 2015 to 2017). "Therefore, the upregulation of RAB25 in renal cell carcinoma may promote tumor development." (PMID 25351113, 2015).
carcinoid (1 paper, 2015). "Studies have indicated that recycling members (Rab11a, Rab11b, Rab25/Rab11c as well as their effectors) exert an important role in cancers of multiple lineages, including breast, colon, lung, ovarian, renal, endometrial, prostate, bladder and carcinoid types." (PMID 25815277, 2015).
chlamydial infection (1 paper, 2016). "During a chlamydial infection, however, endogenous sortilin is localised to the mCherry-Rab25-positive inclusions from 12 hpi." (PMID 26962046, 2016).
clear cell carcinomas (1 paper, 2024). "Interestingly, a description of a ‘glycogen-addicted’ signature in clear cell carcinomas includes overexpression of common mediators of the glycogenesis pathway (i.e. RAB25, GLUT1, protein kinase B (AKT), GSK3, and AMP-activated protein kinase)." (PMID 39479019, 2024).
diffuse peritoneal malignant mesothelioma (1 paper, 2008). "RAB25 was among a group of genes whose overexpression distinguished ovarian/primary peritoneal serous carcinoma (OC/PPC) from diffuse peritoneal malignant mesothelioma (DMPM), two highly aggressive tumor types which are closely related, both morphologically and histogenetically." (PMID 18822129, 2008).
esophageal cancer (1 paper, 2013). A primary or metastatic malignant neoplasm involving the esophagus. "In agreement with colon and esophageal cancer studies, our results in HNSCC showed that low RAB25 expression was associated with poor survival." (PMID 24403269, 2013).
gastric disease (1 paper, 2025). "To verify whether neutralization of TGFA can prevent gastric disease in KO mice, we also implanted the osmotic pumps in 9-month-old Rab25 KO mice." (PMID 41365858, 2025). "Furthermore, long-term exposure to TGFA/EGFR signaling in Rab25 KO mice can induce gastric disease." (PMID 41365858, 2025).
head and neck carcinoma (1 paper, 2013). A carcinoma that arises from the head and neck region. "Our findings show that RAB25 expression is associated with clinical outcome in patients with locally advanced head and neck carcinoma." (PMID 24403269, 2013).
hepatocellular carcinoma (1 paper, 2017). A malignant tumor that arises from hepatocytes. "Depletion of Rab25 inhibited the expressions of Wnt pathway target genes, including cyclin D1, c-Myc and MMP7 in hepatocellular carcinoma." (PMID 28969096, 2017).
hypospadias (1 paper, 2024). Hypospadias is the displacement of the urethral meatus on the ventrum of the penis. "Comparative studies of foreskin tissue from patients with hypospadias and normal children have revealed significant downregulation of Rab25 and Mafb expression in the hypospadias group." (PMID 39698037, 2024).
liver fibrosis (1 paper, 2024). "While previous studies have indicated that certain proteins, including RAB25, may stimulate the activation of hepatic stellate cells in liver fibrosis, the involvement of these factors in pulmonary fibrogenesis remains largely unknown and necessitates further exploration." (PMID 39062997, 2024).
malignant melanoma (1 paper, 2018). "The activation transcription factors, which regulate SPRR1A (small proline rich protein 1A), KRT78, claudin 4 and RAB25 (a member of the RAS oncogene family), also play crucial roles in malignant melanoma metastasis." (PMID 29377892, 2018).
metastatic tumors (1 paper, 2023). "Among the selected candidates, MUC4 was significantly up-regulated in both primary and metastatic samples of fast-progressing patients, whereas HTRA2 and RAB25 were significantly elevated only in primary samples and EPCAM only in metastatic tumors of the fast-progressing group." (PMID 36527824, 2023).
Ménétrier’s disease (1 paper, 2025). "We assessed RAB25 expression levels in a patient with Ménétrier’s disease characterized by massive foveolar hyperplasia." (PMID 41365858, 2025). "The result showed that the RAB25 expression was lower in Ménétrier’s disease than in inflamed normal." (PMID 41365858, 2025). "Nevertheless, a limitation in the present study is that it was not possible to show the direct evidence connecting loss of Rab25 and progression of Ménétrier’s disease." (PMID 41365858, 2025). "Overall, the pathological phenotype seen in Rab25 KO mice resembles Ménétrier’s disease." (PMID 41365858, 2025). "Taken together, Rab25 loss can promote pit cell commitment by enhancing TGFA secretion in gastric epithelial cells, and excessive TGFA secretion due to loss of Rab25 can cause EGFR activation and lead to a stomach phenotype resembling human Ménétrier’s disease." (PMID 41365858, 2025). "Moreover, RAB25 expression was reduced in human Ménétrier’s disease." (PMID 41365858, 2025).
microvillus inclusion disease (1 paper, 2015). Microvillus inclusion disease (MVID) is a very rare, severe, malabsorbative syndrome characterized clinically by protracted or intractable neonatal secretory diarrhea and histologically by inclusion bodies on the intestinal epithelium. "Mutations in MYO5B encoding Myosin 5b, which acts as a molecular motor not only for Rab11a, but also Rab11b, Rab25, and Rab8, cause MicroVillus Inclusion Disease (MVID) in which malabsorption results from the absence of the intestinal brush border." (PMID 26116792, 2015).
oral cavity cancer (1 paper, 2015). A primary or metastatic malignant neoplasm involving the oral cavity. "However, extrapolation of this observation to tongue OSCC, which is the focus of this study, is premature since oral cavity cancers represented less than 10% of the HNSCC cases investigated in the previous studies addressing Rab25." (PMID 26110570, 2015).
pancreatic ductal adenocarcinoma (1 paper, 2024). An infiltrating adenocarcinoma that arises from the epithelial cells of the pancreas. "Meanwhile, CLIC3 and Rab25 collaborate to promote aggressiveness of pancreatic ductal adenocarcinoma through recycling integrin." (PMID 38182571, 2024). "Besides, previous studies report that CLIC3 colocalizes with Rab25 and integrin in late endosomes/lysosomes to promote the migration and invasion of pancreatic ductal adenocarcinoma." (PMID 38182571, 2024).
pancreatic endocrine neoplasms (1 paper, 2013). "RAB25 was also underexpressed in metastatic as compared to non-metastatic pancreatic endocrine neoplasms." (PMID 24403269, 2013).
Parkinson disease (1 paper, 2015). A progressive degenerative disorder of the central nervous system characterized by loss of dopamine producing neurons in the substantia nigra and the presence of Lewy bodies in the substantia nigra and locus coeruleus. "A meta-analysis of genome-wide association studies showed that a common variant at the SYT11/RAB25 locus is associated with Parkinson's disease in Caucasians17, suggesting a role for this gene in neurodegenerative diseases." (PMID 25773295, 2015).
skin cancer (1 paper, 2018). "Almost all skin cancer cell lines had high expression levels of ZEB2 and low levels of RAB25." (PMID 30445998, 2018).
small cell lung carcinoma (1 paper, 2018). Small cell lung cancer (SCLC) is a highly aggressive malignant neoplasm, accounting for 10-15% of lung cancer cases, characterized byrapid growth, and early metastasis. "Correlation between ZEB2 (y-axis) and RAB25 (x-axis) expression from CCLE cell panel datasets analyzed for (a, b) breast (c) colon (d) pancreas, (e) small-cell lung, (f) skin and (g) non-small-cell lung cancer cells." (PMID 30445998, 2018).
spindle cell carcinoma (1 paper, 2024). "Although we have used a small group of patients for the study, we obtained a highly significant result for RAB25 loss in spindle cell carcinoma cases." (PMID 38803515, 2024). "Our study shows that Rab25 loss is strongly associated with spindle cell carcinoma, and 92% of our tumor samples were negative for RAB25 expression." (PMID 38803515, 2024). "We looked at the presence of H-RAS or K-RAS mutations in three of the mammary spindle cell carcinoma cases that were negative for RAB25 expression." (PMID 38803515, 2024).
viral infection (1 paper, 2020). "Together, we showed CSFV infection down-regulates miR-140, and up-regulates Rab25 expression at the early stage of viral infection." (PMID 32114898, 2020).
cancer (75 papers, 2006 to 2025). A tumor composed of atypical neoplastic, often pleomorphic cells that invade other tissues. "The Rab11 family (Rab11a, Rab11b, and Rab25) controls the return of internalized cargos to the plasma membrane, and Rab25 has been implicated in the aggressiveness of cancer by promoting invasive migration." (PMID 40614209, 2025). "In this study, we show that with RAB25 loss and the presence of mutant H-Ras61L, cells lose E-cadherin expression and undergo epithelial-to-mesenchymal transition, a critical process in cancer progression and metastasis." (PMID 38803515, 2024). "An example of a cancer-associated regulator of glycogen is the oncogene RAB25 gene, which up-regulates HIF-1α activity in an oxygen-independent manner, and HIF-1α and hypoxia are shown to enhance glycogen concentration." (PMID 39479019, 2024). "Rab25 belongs to Rab-GTPase family, in which protein dysregulation causes various pathophysiological diseases including cancer." (PMID 34868916, 2021). "Currently, it has been reported that the aberrant expression of Rab25 was linked to cancer development and Rab25 is recognized as an oncogene." (PMID 32114898, 2020). "Accumulating studies have shown the aberrant expression of Rab25 in various human cancers and also indicated its associations with carcinogenesis, cancer progression and patients’ outcome." (PMID 28400705, 2017). "After that, accumulating studies have revealed the aberrant expression of Rab25 and its associations with development, progression and prognosis of numerous types of human cancers." (PMID 28400705, 2017). "The Rab11 family (Rab11a, Rab11b and Rab25) is associated with recycling endosomes, and only Rab25 was previously reported as being associated with cancer." (PMID 29285267, 2017). "Expression of Rab25 was associated with significant increases in ErbB2 protein levels in a panel of difference cancer cell lines including A2780, SKOV3, A549 and U251 cell lines." (PMID 26967059, 2016). "Further, increased Rab25 is associated with poor patient outcome in lung, clear cell renal and bladder cancers likely through effects on metastatic pathways." (PMID 27259233, 2016). "More extensively characterized Rab proteins such as rab25 and rab21 were shown to be associated with increase in tumor cell proliferation and are required to promote cancer cell invasion." (PMID 22920728, 2012). "Another Rab11 family member, Rab25, is associated with aggressive cancers, and drives invasion by binding to α5β1 to control its recruitment to the tips of invasive projections." (PMID 22197222, 2012). "Furthermore, these proof-of-principle data demonstrate the power of our approach using magnets in combination with genetic perturbation to demonstrate the causal effect of Rab25 endosome positioning on F-actin protrusions in invasive cancer cells." (PMID 40614209, 2025). "Aberrant expression of Rab25 was linked to cancer development." (PMID 28969096, 2017). "These expression profiles should provide hypotheses to further explore the downstream pathways enacted by RAB25 function and their link to pathogenic phenotypes in certain cancers." (PMID 28939823, 2017). "A good number of Rabs have been implicated or associated with various human cancers, and much recent excitement has been associated with the roles of the Rab11 subfamily member Rab25 and its effector, the Rab coupling protein (RCP), in tumourigenesis and metastasis." (PMID 25472813, 2015). "Rab25, a member of the Rab11 subfamily that is highly expressed in the epithelial cells of the gastrointestinal tract, lungs and kidney, has in the past few years been implicated in cancers from multiple organs." (PMID 25472813, 2015). "Several Rab proteins including Rab25 have been implicated in multiple cancers." (PMID 23698755, 2013).